BRCA1 (BRCA1 DNA repair associated)
Diseases named in the same sentence as BRCA1 in open-access papers (continued):
Sharing a sentence is not in itself a finding about the gene and the disease.
tumor (continued). "The loss of promoter methylation in BRCA1, which can occur through active demethylation or the positive selection of less methylated tumour cells, may also contribute to PARPi resistance by recovering BRCA1 function and reactivating HRR." (PMID 39796639, 2024). "Therefore, we described how BRCA1/2 tumor testing is performed in 999 EOC patients in the Netherlands in 2019 using real-world clinical data." (PMID 38730634, 2024). "In addition to functioning as a transcription factor, BRCA1 is also a tumor suppressor directly involved in the repair of DNA DSBs and the maintenance of genomic stability." (PMID 38627785, 2024). "Notably, the somatic NGS panel can offer other information with clinical relevance, such as the presence of mutations in BRCA1, BRCA2, PALB2, ERBB2, and ESR1, in addition to molecular changes that can be treated with tumor-agnostic therapies." (PMID 38952553, 2024). "These tumours may have a BRCA1/2 wild type/HRD-positive genotype, although this remains unknown as routine genomic instability score (GIS) testing was not available during most of the study period." (PMID 39550490, 2024). "BRCA1/2 suppresses tumor formation and progression, and recent studies have reported that CagA may prevent the inhibitory effect of BRCA1/2 on HBOC development." (PMID 39590127, 2024). "Therefore, PARPi-resistant Brca1-def and Bard1-def tumor cells expressing either control (Con) or Flt1-specific guide RNA (Flt1i) were exposed to recombinant PGF in vitro." (PMID 38956205, 2024). "Therefore, the clinical relevance of BRCA1 promoter methylation for the response to cisplatin chemotherapy in vivo has been investigated both in tumor xenografts and in clinical studies." (PMID 38256203, 2024). "BRCA1 plays a role in maintaining genomic stability, acting also as a tumor suppressor." (PMID 39683594, 2024). "But it was evident from the immunofluorescence analysis of BRCA1 that DDMSNP was able to reduce post-EMT metastasis of tumor cells to lungs in both 4T1 and CSCs-injected tumor-bearing mice, which was just opposite to our previous result where we found DOX induced post-EMT metastasis." (PMID 38796426, 2024). "Inhibition of PARP-1 could improve CRC chemotherapy beyond defects of BRCA1/2, leading to synergistic cytotoxicity in tumor cells." (PMID 39456536, 2024). "Panel testing allows for the screening of multiple genes beyond BRCA1 and BRCA2 that may be associated with tumor development and/or treatment response." (PMID 39237557, 2024). "Moreover, our RNA‐seq analysis unveiled a notable reduction in the expression of genes crucial for cell proliferation and tumor genesis, such as Ki67 and BRCA1/2, following cisplatin administration." (PMID 39206413, 2024). "Moreover, Werner and Bruchim (2012) reviewed the interactions between IGF and BRCA1 signaling pathways, emphasizing the convergence of IGF1-mediated cell survival, proliferative pathways and BRCA1-mediated tumor suppressive pathways." (PMID 38612922, 2024). "The simultaneous analysis of tumor and germline samples allowed the identification of somatic variants present in low frequency (<10%), and the detection of LOH in tumors from six patients with germline pathogenic/likely pathogenic variants in BRCA1 or BRCA2." (PMID 38308422, 2024). "This term denotes a phenocopy of BRCA1 or BRCA2 variants, a situation in which an HRR defect exists in a tumor in the absence of germline BRCA1 or BRCA2 changes." (PMID 38397209, 2024).
tumor (continued). "Compared to BRCA1-non-altered patients, gBRCA1m patients had a higher incidence of second primary tumors (adjusted subdistribution HR, 4.04; 95% CI, 2.29–7.13), while tumor BRCA1-PM patients had a lower incidence of second primary tumors (adjusted subdistribution HR, 0.42; 95% CI, 0.19–0.95)." (PMID 38191387, 2024). "OTI-611 is cytotoxic to TNBC tumor organoids, potently inhibiting the viability with half maximal inhibitory concentration (IC50) values of 1.7 μM (BRCA1-mutant HR-deficient SUM149PT), 2.8 μM (BRCA1-mutant HR-deficient HCC1937), and 3.3 μM (BRCA-wildtype HR-proficient MDA-MB-231)." (PMID 39201277, 2024). "BRCA1 and BRCA2 genes are typically classified among DNA repair genes, playing a regulatory role in the cell cycle by encoding proteins involved in responding to DNA damage, and hence, acting as tumour suppressor genes." (PMID 39594243, 2024). "BRCA1 and BRCA2 mutations are the pathogenic variants of BRCA that cause loss of function in BRCA1/2 genes and result in genomic instability and tumor development, which might have been the case in our patient." (PMID 39156267, 2024). "Thus, for TNBC, the incidence of BRCA1 tumor epimutations is around two-fold higher than the combined incidence of somatic (sBRCA1) and germline (gBRCA1) mutations." (PMID 40225940, 2024). "Alcohol stimulates the migration and invasion of the BC cell line MCF7, the EMT, vascular development, cellular oxidative stress (OS) and rendering of reactive oxygen species, with decreased levels of E-cadherin, α, β and γ catenin protein and the BRCA1 gene, which suppresses tumor expression." (PMID 38612922, 2024). "We also quantified the % of BRCA1 foci-positive tumor cells (BRCA1/GMN+ cells) in the same samples." (PMID 39039067, 2024). "Gene panel testing allows for the analysis of multiple genes beyond BRCA1 and BRCA2 that may also be associated with tumour development and/or treatment response, and their feasibility for guiding BC treatment is being considered in clinical trials." (PMID 39215191, 2024). "BAP1 is a tumor suppressor that regulates the BRCA1 growth control pathway." (PMID 39272712, 2024). "In tumor cells treated with tamoxifen, abundant lncRNA transcripts of ERs mediate the activating mutations for crucial genes of the genome stabilizer circuit; such as ESR1, BRCA1, and CYP19A." (PMID 38672654, 2024). "Future investigations can assess whether tumor cells expressing mutant BRCA1 exhibit unique sensitivity to BRCA1 downregulating compounds." (PMID 38993666, 2024). "BRCA1 is a large multifunctional protein (1863 amino acids in size) composed of diverse domains essential for its important role in maintaining genomic stability and tumor suppression." (PMID 38543119, 2024). "As a result, H2AX loss restores replication fork stability and increases chemoresistance in BRCA1/2-deficient tumour cells without restoring homology-directed DNA repair, as highlighted by the lack of DNA damage-induced RAD51 foci." (PMID 38789420, 2024). "Moreover, tumor immune infiltration and PD-L1 expression was positively associated with HRR or BRCA1/2 mutation (all P < 0.001)." (PMID 39026672, 2024). "In addition to the analysis of BRCA1/2 in tumour samples, some assays also include measurement of HRD by NGS analysis of genome-wide SNPs, including assessment of loss of heterozygosity (LOH) and/or other markers of genomic instability." (PMID 38443545, 2024). "For hereditary cancers, the approved PARPi indications for breast, ovarian, pancreatic, and prostate malignancies rely on the fact that, in these tumor types, the germline BRCA1/2 alteration is almost always accompanied by somatic second-hit inactivation of the remaining allele." (PMID 38612902, 2024).
tumor (continued). "Again, we did not identify any obvious DSBs in these tumor cells, suggesting that under the low dose treatment of DNA-PK-i and PARP-i, it is ribosome biogenesis impairment but not induced DSBs suppress BRCA1-deficient tumor cell growth." (PMID 38682589, 2024). "Notably, the response rate with the combination of niraparib and pembrolizumab was 19% among patients with BRCA1/2 wild-type tumours, which compares favourably to previously reported ORR of less than 10% with either agent as a monotherapy in this population." (PMID 37430137, 2023). "However, when BRCA1 is mutated, VEGF will be overexpressed to promote tumorigenesis and tumor development." (PMID 37114130, 2023). "For instance, the report of exome sequencing came from a cohort of 347 with over 2/3rds of tumours >51years at diagnosis and no BRCA1/2 variants were reported in 30 metaplastic tumours." (PMID 37592173, 2023). "Interestingly, these data demonstrated that CRISPR KO of FBXO9 led to a CERES project score of ~−0.2; this trend is similar to BRCA1 and BRCA2, which are well-known tumor suppressors associated with DNA damage repair." (PMID 38136595, 2023). "This issue is particularly relevant in HGOC patients, in whom the prevalence of germline BRCA1/2 PVs is estimated to be as high as 10–15%10,22,23, but it could also affect other BRCA-associated tumours, including advanced prostate cancer." (PMID 37179432, 2023). "Seven-hundred-two patients successfully underwent both germline and tumour BRCA1/2 testing." (PMID 36765687, 2023). "Despite this, MIP is a candidate tumor suppressor, while BRCA1 and VHL are known tumor suppressors." (PMID 37742294, 2023). "Moreover, E2F6 was proven to repress a set of tumor suppressors including BRCA1 genes via covalent histone modification." (PMID 36855110, 2023). "This has offered a therapeutic vulnerability that has been extensively explored clinically in BRCA1/2 mutant patients but is now also being examined as a viable therapy in tumours with other specific genotypes, including those presenting with ATM, PALB2, RAD51C, and RAD51D mutations." (PMID 36980782, 2023). "Analysis of the research set of samples, consisting of pairs of normal and tumor breast tissues from unselected patients, allowed us to find all the physiological mRNA junctions for the BRCA1 and BRCA2 genes that were previously identified in the validation set." (PMID 37046838, 2023). "Despite their limitations, both tests remain highly effective in identifying patients who benefit from PARPi treatment in the absence of BRCA1/2 tumor mutation, as observed by PFS analyses." (PMID 37945748, 2023). "Similarly, expression levels for various immune cell markers such as CD3, CD4, and CD8 were highest in the Brca1-null tumours." (PMID 38017453, 2023). "Description of BRCAX tumours has also been difficult with explorative studies general of modest size, with marked variability of inclusion criteria, and are often historically composed of genetic testing limited to BRCA1/2 only." (PMID 36831687, 2023). "The benefit for monotherapy PARPi was observed to be consistent in germline BRCA1/2 mutation carriers across different tumour types regardless of the number of lines of therapy." (PMID 37190285, 2023). "Several strategies have been developed to distinguish BRCA-like from non-BRCA-like tumours, including detection of BRCA1 mutation, genomic scar assays or functional testing of HR capacity by measurement of RAD51 foci." (PMID 37029129, 2023). "Our results suggest that BRCA1/2 function in the HR-dependent bypass of lesions that block DNA replication and that this repair pathway is used to reduce APOBEC-induced mutations in tumor cells, helping to define some of the genetic components of this pathway." (PMID 37532520, 2023).
tumor (continued). "Additionally, cells of a tumor patient-derived ex vivo culture, with low BRCA1 and 53BP1 expression, wereresistant to olaparib or carboplatin butsensitive to ART558." (PMID 37134182, 2023). "In addition to BRCA1/2, only PALB2 and RAD51 paralogs inactivation was shown to be consistently associated with tumor HRD in small but noticeable proportion of cases." (PMID 37945748, 2023). "BRCA1 and BRCA2 are tumor suppressor genes that encode proteins, which are responsible for repairing disruptions in damaged DNA that could otherwise result in tumor formation." (PMID 37185387, 2023). "The epigenetic silencing of BRCA1 was present in both germline and tumor DNA." (PMID 36112334, 2023). "We demonstrated that the activation of Fgfr2 signaling could initiate tumor formation by suppressing Brca1 via the ERK-YY1 axis." (PMID 37063417, 2023). "The BRCA1 gene provides instructions to produce a protein that acts as a tumor suppressor." (PMID 37511023, 2023). "Matched tumour-normal BRCA1/2 testing can be costly and logistically challenging." (PMID 38201604, 2023). "NRF2, activated by BRCA1, increased phase-II enzymes and abrogated tumor progression." (PMID 37571283, 2023). "By contrast, 3 out of 8 germline BRCA1/2 pathogenic large rearrangements were not reported in tumour DNA." (PMID 38201604, 2023). "Costs for patients treated with olaparib, enzalutamide, or abiraterone increased substantially in the subgroup of patients with a tumor harboring at least one of three prespecified gene alterations (BRCA1, BRCA2, or ATM) versus those with at least one of 15 prespecified gene alterations." (PMID 37829336, 2023). "However, when PARP 1 and 2, key enzymes of the alternative pathways involved in double-stranded DNA repair are blocked with PARP inhibitor, it will result in the instantaneous BRCA1 mutant tumour cell death." (PMID 37680708, 2023). "PARP inhibitors target DNA repair pathways that BRCA1/2-mutant tumours are dependent upon." (PMID 37190285, 2023). "Moreover, we were able to identify a number of genes in addition to BRCA1/2 that lead to cisplatin sensitivity and confirmed that most tumours sensitive to cisplatin have DNA repair defects." (PMID 37029129, 2023). "Taking advantage of Gata3 and Brca1 deficient tumor cells lacking Gata3 and expressing high level of Fra1, we knocked out Fra1 in these cells by using the CRISPR/Cas9 system." (PMID 37353480, 2023). "This implies that BRCA1 status and tumor hypoxia should be considered as crucial clinical parameters that could influence the efficacy of HDAC inhibitors as therapeutic agents." (PMID 37762577, 2023). "In our cohort, which included 203 HGOC women who had not undergone prior germline analyses, 45 patients showed BRCA1/2 pathogenic or likely pathogenic variants (henceforth termed as PVs) at tumour testing (31 BRCA1, 14 BRCA2)." (PMID 37179432, 2023). "In contrast to tumours with BRCA1 or BRCA2 driver events, which harboured 1.6x (95% CI, 1.0–2.4x) and 1.4x (95% CI, 0.9–1.9x) more SVs as well as excess of 10–100 bp deletions (BRCA1, 2.2x; BRCA2, 7.3x), SPOP tumours did not display excess of other somatic mutation types." (PMID 37420249, 2023). "In addition, exogenous BRCA1 attenuated cisplatin-induced downregulation of miR-593-5p, with an inhibitory effect on mitochondrial fission and apoptosis induction in tumor cells." (PMID 36827549, 2023). "A similar sensitivity may be found in tumours with molecular changes that mimic the BRCA mutated phenotype, such as BRCA1 epigenetic inactivation or mutations in other genes involved in DNA DSB repair." (PMID 37029129, 2023).
tumor (continued). "There was a significant difference in tumor morphology between BRCA1 and BRCA2 tumors (p < 0.001)." (PMID 36905492, 2023). "Furthermore, the relevance of tumor grade as a prognostic factor for BRCA1/2 has been questioned repeatedly." (PMID 37173335, 2023). "Especially, the prognostic impact of the tumor grade deviated highly significantly from the PREDICT model, possibly reflecting underlying differences in the impact of tumor grade on prognosis in BRCA1/2 carriers when compared to the patient populations on which the PREDICT model is based." (PMID 37173335, 2023). "Therefore, we next tested the inhibitory effects of thioparib in a panel of tumor cell lines harboring BRCA1−/−, BRCA2−/−, PTEN−/−, or EWS‐FLI1 gene fusion." (PMID 36652375, 2023). "We identified 193 tumor samples with BRCA1 promoter hypermethylation in 178 unique patients." (PMID 36112334, 2023). "The hypoxic tumour microenvironment brought about by antiangiogenic agents (such as bevacizumab and cediranib) is thought to downregulate the expression of key gene products involved in homologous recombination repair (BRCA1/2 and RAD51)." (PMID 37108451, 2023). "Of 60 evaluable patients, 58 (97%) exhibited ≥1 BRCA1 or BRCA2 pathogenic tumor mutation (tBRCA1/2mut); no patients had both BRCA1 and BRCA2 mutations." (PMID 37803017, 2023). "Their study population of non-BRCA1/BRCA2 tumours had a similar sample size to our study." (PMID 37316882, 2023). "As a tumor suppressor gene, BRCA1 has an established role in DNA repair process." (PMID 37387166, 2023). "The three germline BRCA1/2 pathogenic variants not detected in tumour DNA were all large rearrangements and included two BRCA1 Exon 13 duplications (n = 2) and a BRCA2 Exon 1–24 deletion (n = 1)." (PMID 38201604, 2023). "In the PAOLA trial, 29/114 patients (25.4%) and, in the AGO TR-1 study, 31/393 patients (7.9%) with a BRCA1/2 mutation in the tumor had no mutation in the germline, respectively." (PMID 36765776, 2023). "Further germline testing was deemed appropriate in mCRPC patients having a BRCA1/2 tumour (L)PV." (PMID 36874601, 2023). "As a protective mechanism, the tumor suppressor gene breast cancer susceptibility gene 1, also known as BRCA1, interacts with ACCA and stabilizes the inactive state, which prevents tumor cell anabolism, suppresses the malignant phenotype, and raises Acetyl-CoA levels." (PMID 37623881, 2023). "However, in the TNT trial, no benefit of carboplatin over docetaxel was observed in mTNBC patients with BRCA 1 methylation, BRCA1 mRNA-low tumors, or in patients whose tumor harbored other HRD features, such as a high HRD score (by the Myriad assay)." (PMID 36831640, 2023). "While concordant BRCA1 methylation in tumor tissue and matched blood samples may suggest a common clonal origin, we sought to provide further evidence for this hypothesis by assessing the allele specificity of the BRCA1 methylation in tumors and blood." (PMID 38053165, 2023). "A detailed analysis of the TME revealed that olaparib monotherapy resulted in a large number of immunosuppressive and immunomodulatory effects in the more inflamed Brca1-deficient TME but not Brca2-deficient tumours." (PMID 38017453, 2023). "As of yet, while there is a theoretical advantage in combined pharmacological therapy in HER2-positive tumours occurring in BRCA1/2 mutation carriers, there is no definitive guidelines or data pertaining to this population." (PMID 36831687, 2023). "Also, if a substitute pathway is available to repair damaged DNA, BRCA1 mutant tumours will tolerate homologous recombination defects." (PMID 37680708, 2023). "In this age group, it may be more appropriate to focus resources on reflex BRCA1/2 and HRD tumour testing, with confirmatory germline BRCA1/2 testing reserved for those patients with a tumour-pathogenic variant." (PMID 36765687, 2023).